LINC02870 (long independently transcribed non-coding RNA 2870)
Synonyms: bA432J24.4; C10orf91
Gene: Long non-coding RNA gene on chromosome 10 (132,444,311 to 132,449,408, forward strand). Ensembl gene ENSG00000180066.
Diseases named in the same sentence as LINC02870 in open-access papers:
LINC02870 is named in the same sentence as 5 diseases in open-access papers, as found by Europe PMC text mining. Sharing a sentence is not in itself a finding about the gene and the disease.
LINC02870 shares sentences with these, for which no sentence is quoted: cancer (1 paper); cutaneous squamous cell carcinoma (1); endometrial adenocarcinoma (1); oral squamous cell carcinoma (1); tumor (1).